GAS6 (growth arrest specific 6)
Diseases named in the same sentence as GAS6 in open-access papers (continued):
Sharing a sentence is not in itself a finding about the gene and the disease.
Sepsis (continued). "Overall, our data suggest that plasma Gas6 level measurement could be useful to stratify patients with sepsis." (PMID 27788141, 2016). "Recent studies indicate that Gas6 influences host responses to endotoxemia and bacterial infection by modulating innate immunity and may have thereby a protective role during sepsis." (PMID 27788141, 2016). "The main effects of the Gas6 signaling in sepsis remain to be determined." (PMID 20731857, 2010). "Gas6 is involved in several systems, which are active during sepsis." (PMID 20731857, 2010). "The product of growth arrest-specific gene 6 (Gas6) recently attracted attention because it was found to be elevated during sepsis and may correlate with organ dysfunction." (PMID 17241453, 2007). "Evidence of a role for the Gas6/Axl system during sepsis has been obtained in mice." (PMID 17241453, 2007). "Gas6 may not be a reliable indicator of vitamin K deficiency, but potentially a marker of disease severity in sepsis patients." (PMID 38956732, 2024). "Furthermore, Gas6 may attenuate neutrophil infiltration into the lungs during sepsis, which is crucial in acute lung injury." (PMID 38956732, 2024). "Therefore, Gas6 may be an interesting therapeutic strategy for recovery from sepsis and a suitable therapeutic option for sepsis." (PMID 31263416, 2019). "Studies reveal suppressed GAS6 expression and diminished AMPK activity in sepsis-induced myocardial injury, while exogenous restoration of this pathway effectively improves cardiac dysfunction." (PMID 40872581, 2025). "The activation of Gas6-AXL signaling has been showed to provide protection against ischemia–reperfusion injury and sepsis induced injury." (PMID 40933570, 2025). "Moreover, Gas6 administration could be envisaged as a therapeutic reinforcement to the current treatment, since it showed to be able to ameliorate the overall survival and to partially protect from the organ dysfunction in a mouse model of sepsis." (PMID 31485279, 2019). "Due to this involvement, many authors have demonstrated the pivotal role of the Gas6/TAM axis in both sepsis and the sepsis-related inflammatory responses." (PMID 31485279, 2019). "However, Gas6 might also contribute to the hypo-inflammatory response in a later phase of sepsis and participate to a compensatory anti-inflammatory response syndrome that might results in immunoparalysis with inability to clear the original pathogen invasion or predisposes to secondary infection." (PMID 27788141, 2016). "In many different clinical conditions, including sepsis, CLI and SLE, the concentrations of Gas6 and sAxl demonstrate strong correlation to inflammatory markers suggesting that both Gas6 and Axl expression increases as part of the acute inflammatory response." (PMID 21496228, 2011). "The patients with severe sepsis, sepsis, infection or SIRS had all increased concentrations of Gas6, approximately double compared to what was found in the controls." (PMID 20731857, 2010). "Additionally, while this study confirms the essential role of the GAS6/AXL pathway in microglia, its behavior in various sepsis models and human clinical samples requires further validation." (PMID 40480981, 2025). "Both sMer and Gas6 independently predicted thrombocytopenia in sepsis patients not treated with anticoagulants (OR 1.01 [1.00–1.02] and 1.04 [1.02–1.06], respectively)." (PMID 35203408, 2022). "Most sepsis studies have failed to correlate Gas6 with mortality, whereas a prospective cohort study did." (PMID 34836355, 2021). "According to these findings, Gas6 cannot predict sepsis evolution, unlike other inflammatory mediators, such as TNF-α and IL-1β." (PMID 31485279, 2019). "In conclusion, the Gas6/TAM axis activation possibly ameliorates the tissue hypoperfusion, thus restoring the physiological tissue homeostasis and preserving organ function, with a positive impact on sepsis prognosis." (PMID 31485279, 2019).
Sepsis (continued). "A major difference between Gas6 and currently used predictors of sepsis evolution, such as cytokines, is the absence of time-survival interaction." (PMID 27788141, 2016). "Two previous studies have found increased concentrations of Gas6 in sepsis, but its relation to sAxl concentrations has not been investigated." (PMID 20731857, 2010). "The plasma concentrations of Gas6 and sAxl were determined in the acutely ill patients who were found to suffer from severe sepsis, sepsis, infections without SIRS, or SIRS without infection." (PMID 20731857, 2010). "Clinically, GAS6/AXL pathway activators or related drugs could offer a novel therapeutic strategy for treating SAE by enhancing microglia’s anti-inflammatory and clearance capabilities, potentially improving neurological outcomes in sepsis patients." (PMID 40480981, 2025). "At this point, the exact role of Gas6 in sepsis is not well understood, nor is it known whether interactions with Axl in microvascular EC contribute to morbidity and/or mortality in sepsis patients." (PMID 35634305, 2022). "Altogether, our findings indicate that combined treatment with Gas6 and antibiotics ameliorates sepsis-induced organ damage and reduces systemic LDH levels in mice, suggesting that Gas6 intravenous injection may be a viable therapeutic option in sepsis." (PMID 33803290, 2021). "Growth arrest-specific 6 (Gas6) is expressed in leukocytes, platelets, endothelial cells, and monocytes, and increased serum levels have been described in patients with sepsis and septic shock; it is considered a general marker of inflammation rather than a specific biomarker of sepsis." (PMID 31661804, 2019). "In this study published in 2017, the authors enrolled 129 patients with a diagnosis of sepsis and they compared the patients with and without ALI, observing that Gas6 levels, together with IL-6 and IL-8 levels, were significantly elevated among patients who developed ALI." (PMID 31485279, 2019). "We have measured the Gas6 and sAxl plasma concentrations in a large cohort of patients with severe sepsis, sepsis, milder infections, and SIRS without infection, and found that Gas6 increases in all patient groups, and the concentration correlates with disease severity and organ dysfunction." (PMID 20731857, 2010). "Also, non-survivors of sepsis in ICU tend to have initial higher concentration of GAS6 and GAS6 could predict mortality with an area under the curve (AUC) of 0.742." (PMID 34344929, 2021). "Summarizing, on the basis of previous studies, it is possible to hypothesize the use of Gas6 as a biomarker in the complex pathophysiology of sepsis, since several data seem to suggest a role of Gas6 as a useful biomarker for discriminating between noninfectious SIRS, sepsis, and septic shock." (PMID 31485279, 2019).
liver fibrosis (22 papers, 2018 to 2024). "GAS6 is (profibrogenic factor) one of the main receptors in the liver that has been associated with liver fibrosis." (PMID 35743193, 2022). "After chronic CCl4 injury, Gas6-deficient mice also exhibited reduced liver fibrosis as a consequence of defective macrophage recruitment compared with wild-type animals." (PMID 31583026, 2019). "Even more relevant, the diagnostic accuracy of Gas6 was comparable to that of liver elastography both in ruling out and in detecting severe liver fibrosis." (PMID 31583026, 2019). "In conclusion, observations from studies of Gas6 KO mice are in accordance with recent findings in patients and underline Gas6-dependent Axl signaling in liver fibrosis." (PMID 30567378, 2018). "The association between GAS6 and liver fibrosis and autoimmune phenotypes could explain the difference between the AIH cohort and controls regarding GAS6 expression." (PMID 37108648, 2023). "Examining the combination of Gas6 and Axl will clarify the role and mechanism of ectodomain shedding and might strengthen diagnostic and therapeutic strategies to combat liver fibrosis and HCC." (PMID 30567378, 2018). "Although MerTK-targeting in experimental MASH models has demonstrated to reduce liver fibrosis, MerTK was also shown to confer hepatocyte protection against lipotoxicity through Gas6." (PMID 38298195, 2024). "Gas6 and Axl signaling has a particularly relevant role in the development of liver fibrosis, by promoting HSC activation, a key step in fibrotic tissue formation." (PMID 38298195, 2024). "The activation of hepatic stellate cells involves various pathways such as the TGF-β/SMAD, Wnt, and Gas6/Axl signaling pathways, and the development of hepatic fibrosis is very complex." (PMID 38498120, 2024). "Further prospective studies are required to confirm the potential of Gas6/alb as screening marker for liver fibrosis and cirrhosis, and for the prediction of clinical outcome in patients with advanced chronic liver disease." (PMID 37532736, 2023). "Gas/alb outperformed Gas6, sAxl, and sAxl/alb for the detection of biopsy-proven significant to advanced liver fibrosis and cirrhosis." (PMID 37532736, 2023). "Lastly, the key differential ligand-receptor pairs involved in cellular communications were identified and we confirmed the role of GAS6_AXL interaction-mediated cellular communication in promoting liver fibrosis." (PMID 36814339, 2023). "Yet, the role of Gas6 as serum-based screening marker for the detection of liver fibrosis, compensated and decompensated liver cirrhosis, and HCC has remained unclear." (PMID 37532736, 2023). "In fact, the Gas6/TAM system has recently emerged as an important player in the progression of liver fibrosis and as a novel biomarker of liver fibrosis." (PMID 34805276, 2021). "After five weeks of CCl4 treatment, wild-type mice exhibited a marked increase in Gas6 and sAxl serum levels compared to controls, indicating that this pathway is upregulated during CCl4-induced liver fibrosis." (PMID 31583026, 2019). "Different reviews have been published, particularly regarding Gas6’s involvement in the development of liver fibrosis." (PMID 31614787, 2019). "In this context, they have introduced thresholds of plasmatic Gas6 for liver fibrosis (30 ng/mL) and severe fibrosis (42 ng/mL)." (PMID 31485279, 2019). "Recent findings support the idea of Gas6-dependent Axl signaling in liver fibrosis which has been revealed by Gas6 KO and Axl KO studies, showing reduced fibrogenesis." (PMID 30567378, 2018). "Gas6 plays an important role in steatohepatitis and progression to liver fibrosis as Gas6 KO mice show a decreased disease burden." (PMID 30567378, 2018). "Signaling of the receptor tyrosine kinase Axl and its ligand Gas6 is crucially involved in the development of liver fibrosis and hepatocellular carcinoma (HCC) by activation of hepatic stellate cells and modulation of hepatocyte differentiation." (PMID 30567378, 2018).
liver fibrosis (continued). "As described, liver fibrosis predisposes patients for HCC, which indicates that Gas6/Axl represents an oncogenic driver." (PMID 30567378, 2018). "In the current study, we investigated the performance of Gas6 and Gas6/alb for the detection and prediction of significant to advanced liver fibrosis, compensated and decompensated liver cirrhosis, CSPH, transplant-free survival, and HCC in a large Central European multicentric cohort." (PMID 37532736, 2023). "In line with a crucial role of Gas6/Axl in liver diseases, we have previously demonstrated that soluble Axl (sAxl), generated by Axl shedding, is elevated in patients with liver fibrosis and cirrhosis, and may detect early stages of HCC." (PMID 37532736, 2023). "CCl4-induced liver fibrosis activates the Gas6/Axl pathway, which in turn promotes HSC activation." (PMID 34805276, 2021). "Evaluating levels of sAxl and Gas6 from the onset of CLD might be beneficial in monitoring the progression of liver fibrosis and HCC." (PMID 34771611, 2021). "Targeting Gas6 signaling may be a potential treatment for liver fibrosis, so how Gas6 contributes to liver fibrosis should be further explored." (PMID 34805276, 2021). "The relevance of the Gas6/Axl axis in liver fibrosis has also been described in humans." (PMID 32454903, 2020). "GAS6-KO mice also display reduced liver fibrosis induced by chronic carbon tetrachloride treatment." (PMID 32372975, 2020). "In vivo experiments testing whether direct targeting of Axl, Mertk or Tyro3 by using specific TAM inhibitors or by GAS6 neutralizing antibodies can reduce the development of hepatic fibrosis are still underway." (PMID 32372975, 2020). "Consequently, hepatic fibrosis progression should be subsequently attenuated by diminished Gas6/Axl signaling, resulting in a phenotype comparable to the one of chemically challenged Gas6 KO mice." (PMID 31583026, 2019). "The most promising findings up to date acknowledge that both Gas6 and its receptor serum levels (such as sAxl and, probably, sMERTK) have been shown to potentially allow for easy and accurate measurement of hepatic fibrosis progression, also providing indicative parameters of hepatic dysfunction." (PMID 31583026, 2019). "Additionally, deficiency in growth arrest-specific 6 (GAS6), a ligand of MERTK, attenuates hepatic steatosis, inflammation, and liver fibrosis in mouse models." (PMID 30477195, 2018). "Interestingly, this protective effect is not specifically associated to a causal factor, being Gas6 −/− KO mice protected against liver fibrosis also in case of repetitive CCl4 exposure." (PMID 31614787, 2019). "The GAS6/AXL signaling pathway regulates HSC proliferation and activation, which play an important role in liver fibrosis development." (PMID 38069259, 2023). "In the present paper, we have reviewed current evidence regarding the use of Gas6 and its TAM receptors as potential biomarkers of liver fibrosis." (PMID 31583026, 2019). "A study on liver fibrosis showed that AXL and GAS6 are required to induce fibrogenesis by hepatic stellate cells; Accordingly, exposition to bemcentinib reduced liver fibrosis in mice." (PMID 31134766, 2019). "As more experimental and clinical studies are performed to reveal the hepato-carcinogenic roles of Gas6 and TAM, they are expected to uncover a mechanistic link between liver fibrosis and HCC through the Gas6/TAM signaling pathway." (PMID 30700007, 2019). "Gas6/TAM system (mainly, Axl and MERTK) has in fact recently emerged as an important player in the progression of liver fibrosis." (PMID 31583026, 2019). "Our results revealed that the transcripts of DBP and GAS6 were upregulated in liver of HFD-fed mice, confirming that liver fibrosis and NASH might be developed." (PMID 35743193, 2022).
liver fibrosis (continued). "In fact, when compared to WT mice, knocking out Gas6 myofibroblast activation in a murine model of steatohepatitis leads to a reduction of the hepatic expression of TGF-β, collagen 1, and collagen 3 mRNA and prevents the development of liver fibrosis." (PMID 31614787, 2019). "The GAS6/AXL pathway promotes HSC activation and could attenuate hepatic fibrosis." (PMID 37108648, 2023).
pancreatic cancer (21 papers, 2014 to 2025). "Gas6 and its major receptor Axl are abundantly expressed in various cancers, such as ovarian, breast, glioblastoma, gastric, lung, and pancreatic tumor, and their presence is associated with a bad prognosis." (PMID 37313463, 2023). "The Gas6-Axl pathway is active in 70percent of individuals with pancreatic cancer and is linked to a poor prognosis and a rise in the number of distant metastases." (PMID 37313463, 2023). "The Gas6–Axl pathway is activated in 70% of pancreatic cancer patients and is associated with a poor prognosis and increased frequency of distant metastasis." (PMID 32174917, 2020). "This induction occurs through the release of factors such as MCP-1 and Gas6 from TAMs when pancreatic cancer cells are exposed to macrophage-derived exosomes, conditioned media, or are indirectly co-cultured with macrophages." (PMID 40624025, 2025). "GAS6-CAR-T cells efficiently kill TAM-positive pancreatic cancer cell lines, gemcitabine-resistant cancer cells, and cancer stem-like cells in vitro." (PMID 37475048, 2023). "Intravenous administration of GAS6-CAR-T cells led to a significant suppression of pancreatic cancer PDX tumor growth, while tumors in the Mock group continued to grow rapidly." (PMID 37475048, 2023). "We demonstrated that GAS6-CAR-T cells can inhibit the growth of pancreatic cancer PDX models by elimination of both AXL-positive tumor cells and tumor-associated macrophages." (PMID 37475048, 2023). "The role of AXL signaling in progression and metastasis of pancreatic cancer was confirmed in a study using low-dose warfarin, a vitamin K “antagonist” to inhibit Gas6-dependent AXL activation." (PMID 37469409, 2023). "Here, we have shown that GAS6-based CAR-T cells can effectively kill TAM-positive pancreatic tumor cells and inhibit the growth of xenograft tumors in vivo by eliminating both tumor cells and tumor-associated macrophages." (PMID 37475048, 2023). "Chemotherapy increases Gas6 expression in circulating neutrophils from patients with metastatic pancreatic cancer and recombinant Gas6 is sufficient to promote tumour cell proliferation ex vivo, in patient-derived metastatic liver explants." (PMID 35022267, 2022). "We next assessed Gas6 expression in circulating neutrophils in patients with metastatic pancreatic cancer and in our mouse metastases model." (PMID 35022267, 2022). "These experiments suggest that Gas6 is sufficient to promote the regrowth of gemcitabine-treated pancreatic cancer cells not only in PDAC cell lines in vitro, but also in patient-derived metastatic liver samples ex vivo." (PMID 35022267, 2022). "Addition of recombinant Gas6 was sufficient to promote the regrowth of gemcitabine treated human and mouse pancreatic cancer cells." (PMID 35022267, 2022). "In pancreatic cancer cell lines Panc-1 and BxPC-3, 20G7-D9 reduced Gas6-induced Axl and Akt phosphorylation and impaired tumor cell migration, viability, and tumor growth in vivo." (PMID 34576116, 2021). "Gas6 and its main receptor Axl are overexpressed in several cancer types including, breast, ovarian, gastric, glioblastoma, lung, and pancreatic cancer and their expression correlates with a poor prognosis." (PMID 32174917, 2020). "Activation of the tyrosine kinase receptor AXL and expression of its ligand growth arrest-specific protein 6 (Gas6) correlate with a poor prognosis and increased metastasis in pancreatic cancer patients." (PMID 32174917, 2020). "Strategies to target Gas6 have been developed, by blocking antibodies or drugs like warfarin, and are currently in an early Phase 1 clinical trial in patients with pancreatic cancer." (PMID 32708142, 2020). "In conclusion, our studies suggest that in pancreatic cancer, Gas6 is secreted by both TAMs and CAFs and blockade of Gas6 signaling has a dual anti-metastatic effect by acting on both the tumor cells and the NK cells." (PMID 32174917, 2020).